FOXJ1 (forkhead box J1)
Description:
Transcription factor specifically required for the formation of motile cilia. Acts by activating transcription of genes that mediate assembly of motile cilia, such as CFAP157. Binds the DNA consensus sequences 5'-HWDTGTTTGTTTA-3' or 5'-KTTTGTTGTTKTW-3' (where H is not G, W is A or T, D is not C, and K is G or T). Activates the transcription of a variety of ciliary proteins in the developing brain and lung.
Synonyms: HFH-4; FKHL13; HFH4; CILD43
Tractability: No criterion of Open Targets' tractability assessment is met for any kind of drug.
Gene: Protein-coding gene on chromosome 17 (76,136,333 to 76,141,245, reverse strand). Ensembl gene ENSG00000129654.
Subcellular location: Nucleus
Gene Ontology:
Molecular function: protein binding; transcription cis-regulatory region binding; DNA binding; DNA-binding transcription activator activity, RNA polymerase II-specific; DNA-binding transcription factor activity; DNA-binding transcription factor activity, RNA polymerase II-specific; RNA polymerase II cis-regulatory region sequence-specific DNA binding; sequence-specific DNA binding
Biological process: axoneme assembly; ciliary basal body organization; cilium assembly; determination of left/right symmetry; glomerular parietal epithelial cell development; intracellular protein localization; lung epithelium development; metanephric part of ureteric bud development; positive regulation of lung ciliated cell differentiation; positive regulation of transcription by RNA polymerase II; actin cytoskeleton organization; brain development; central tolerance induction; epithelium development; establishment of apical/basal cell polarity; humoral immune response; leukocyte migration; negative regulation of B cell activation; negative regulation of germinal center formation; negative regulation of humoral immune response mediated by circulating immunoglobulin; negative regulation of interleukin-6 production; negative regulation of non-canonical NF-kappaB signal transduction; negative regulation of T cell differentiation in thymus; negative regulation of transcription by RNA polymerase II; pattern specification process; and 7 more
Cellular component: nucleus; chromatin
Genetic constraint (gnomAD): Loss-of-function variants: 8 observed, 20.58 expected, observed/expected ratio (o/e) 0.39, 90% interval 0.23 to 0.7. The upper end of that interval is the gene's LOEUF score, 0.7, which puts it in group 2 of 6, group 1 being the genes least tolerant of losing a copy. Missense variants: 539 observed, 514.77 expected, observed/expected ratio (o/e) 1.05, 90% interval 0.98 to 1.12. Synonymous variants: 280 observed, 245.95 expected, observed/expected ratio (o/e) 1.14, 90% interval 1.03 to 1.26.
Gene-disease validity (ClinGen):
ClinGen rates the evidence that FOXJ1 causes each of these diseases.
ciliary dyskinesia, primary, 43 (autosomal dominant): Definitive.
Homologues: Orthologues: chimpanzee FOXJ1 (99% identical), macaque FOXJ1 (99% identical), pig FOXJ1 (95% identical), rabbit FOXJ1 (94% identical), dog FOXJ1 (94% identical), mouse Foxj1 (93% identical), rat AABR07030823.1 (92% identical), guinea pig FOXJ1 (91% identical), tropical clawed frog foxj1 (63% identical), zebrafish foxj1a (54% identical). Paralogues in human: FOXK2 (23% identical), FOXK1 (22% identical), FOXJ3 (20% identical), FOXD1 (19% identical), FOXI3 (19% identical), FOXJ2 (19% identical), FOXD3 (18% identical), FOXA2 (18% identical), FOXC1 (17% identical), FOXN1 (17% identical), FOXC2 (17% identical), FOXI2 (17% identical), and 29 more.
Diseases named in the same sentence as FOXJ1 in open-access papers:
FOXJ1 is named in the same sentence as 82 diseases in open-access papers, as found by Europe PMC text mining. Sharing a sentence is not in itself a finding about the gene and the disease. The quoted sentences say what the papers report.
Hydrocephalus (27 papers, 2007 to 2025). Hydrocephalus is an active distension of the ventricular system of the brain resulting from inadequate passage of CSF from its point of production within the cerebral ventricles to its point of absorption into the systemic circulation. "A similar phenotype including left–right defects, hydrocephalus, and perinatal mortality is observed in mice deficient in genes regulated by Foxj1 that are commonly deficient in PCD, such as the murine orthologues of DNAH5, DNAI1, DNAAF5, CCDC39, and CCDC40." (PMID 40348912, 2025). "The beating of EPC cilia is the main propelling force for CSF circulation in mice, but only mutations in seven genes, including Foxj1, Mcidas, and Ccno, have been identified as causing hydrocephalus by impairing EPC-lineage differentiation." (PMID 40737354, 2025). "While genetic mouse models of PCD frequently develop hydrocephalus, patients with PCD hydrocephalus are sporadic, except those with mutations in FOXJ1, CCNO, P73, and MCIDAS, indicating developmental differences between rodents and humans." (PMID 38032388, 2024). "Subsequent experiments have confirmed that inhibition of FoxJ1 protein expression leads to ventricular cilia deficiency, resulting in hydrocephalus." (PMID 38337135, 2024). "Genomic sequencing of DNA obtained from patients with hydrocephalus has identified FOXJ1 as a recurrently mutated gene in a subset of individuals." (PMID 37620636, 2023). "Together, these results indicated that haploinsufficiency of Foxj1 causes communicating hydrocephalus in mice." (PMID 37620636, 2023). "Several reports have identified heterozygous FOXJ1 mutations in association with obstructive hydrocephalus in humans." (PMID 37620636, 2023). "Heterozygous mutations affecting FOXJ1, a transcription factor governing multiciliated cell development, have been associated with obstructive hydrocephalus in humans." (PMID 37620636, 2023). "Heterozygous FOXJ1 mutations impair motile cilia structure and basal body alignment, thereby disrupting CSF flow dynamics and causing communicating hydrocephalus." (PMID 37620636, 2023). "In light of our finding that heterozygous FOXJ1 mutation is associated with communicating hydrocephalus in humans and in mice, one must consider the possibility that the patient actually had communicating hydrocephalus." (PMID 37620636, 2023). "Disruption of one Foxj1 allele in mice leads to incomplete ependymal cell differentiation and communicating hydrocephalus." (PMID 37620636, 2023). "Here, we show that heterozygous FOXJ1 mutations are also associated with communicating hydrocephalus in humans and cause communicating hydrocephalus in mice." (PMID 37620636, 2023). "Taken together, our findings shed new light on the possible mechanisms by which heterozygous FOXJ1 mutations cause hydrocephalus in humans and in mice." (PMID 37620636, 2023). "For example, it is possible that different FOXJ1 mutations have different effects, leading to communicating or obstructive hydrocephalus by distinct and unrelated mechanisms." (PMID 37620636, 2023). "Recently, pathogenic variants in FOXJ1 (Chr 17q25.1) were identified causing PCD associated with hydrocephalus, reduced respiratory cilia number, axonemal microtubule disorganization, and occurring in a de novo, autosomal dominant inheritance pattern." (PMID 34132502, 2021). "We report 2 cases of primary ciliary dyskinesia (PCD) with hydrocephalus, both caused by de novo, autosomal dominant, variants in FOXJ1." (PMID 34132502, 2021). "For example, Foxj1 mutation results in ciliopathy and hydrocephalus due to dysfunction of motile cilia." (PMID 35047005, 2021). "Further exploration of ciliary protein involvement in normal human cerebrospinal flow is necessary to explain this delayed onset of hydrocephalus in FOXJ1 associated cases." (PMID 34132502, 2021). "Variants in FOXJ1 are a rare cause of respiratory ciliary dysfunction and hydrocephalus, but few cases have been previously illustrated." (PMID 34132502, 2021).
Hydrocephalus (continued). "Patients with inborn heterozygous mutations in the FOXJ1 gene show a motile ciliopathy with hydrocephalus and a chronic destructive airway disease." (PMID 34272374, 2021). "Heterozygous mutations in FOXJ1, which encodes forkhead transcription factors important for ciliogenesis of motile cilia, cause motile ciliopathy characterized by hydrocephalus, respiratory disease, and randomization of left/right body asymmetry." (PMID 33999288, 2021). "When reported, hydrocephalus in PCD patients is most closely associated with variants in genes resulting in reduced generation of motile cilia (FOXJ1, MCIDAS, TP73, CCNO)." (PMID 35011687, 2021). "Mutations in a key transcription factor that regulates cilia gene expression, FOXJ1, also reduce the number of motile cilia, and are clinically associated with hydrocephalus, recurrent respiratory infections, and laterality defects." (PMID 34361034, 2021). "Limited information is currently known about the role of FOXJ1 in respiratory cilia dysfunction or hydrocephalus in humans, and it is likely quite rare as a cause of PCD." (PMID 34132502, 2021). "Variants in FOXJ1 are most consistently associated with hydrocephalus, with one case series present in all of 11 subjects." (PMID 35011687, 2021). "Repeating these experiments via P30 tamoxifen induction, analyzed 2 weeks later, showed the same Foxj1 cKO mutant EC morphological changes, loss of multicilia and their associated basal bodies, as well as ventriculomegaly/hydrocephalus." (PMID 29695808, 2018). "Knockout of genes expressed in the CPe, such as E2f5, a member of a family (E2f1–E2f6) of transcriptional regulators, FoxJ1, a member of the forkhead-box (Fox)/winged helix gene family, and p73, have been associated with hydrocephalus." (PMID 19114013, 2008). "Knockouts of E2f5, a member of a family (E2f1–E2f6) of transcriptional regulators and FoxJ1, a member of the forkhead-box (Fox)/winged helix gene family, have been associated with defective choroid plexus function resulting in hydrocephalus." (PMID 19114013, 2008). "Investigating whether all perturbations in the upstream signaling of FoxJ1 are associated with hydrocephalus represents a promising avenue for future exploration." (PMID 38337135, 2024). "FOXJ1 loss of function causes left-asymmetry defects and hydrocephalus in mice and humans." (PMID 38032388, 2024). "Together, our findings suggest that heterozygous FOXJ1 mutations can cause either obstructive or communicating forms of hydrocephalus in humans, and they imply the existence of a mechanism contributing to hydrocephalus other than physical obstruction to CSF flow through the ventricular system." (PMID 37620636, 2023). "Published reports have strongly associated heterozygous FOXJ1 mutations with defects in mucociliary clearance, situs inversus, and obstructive hydrocephalus in humans, consistent with the known pattern of expression of this transcription factor in multiciliated epithelia." (PMID 37620636, 2023). "Thus, heterozygous FOXJ1 mutations impair ventricular multiciliated cell differentiation, thereby causing communicating hydrocephalus." (PMID 37620636, 2023). "However, we report here a case of communicating hydrocephalus occurring in the context of heterozygous FOXJ1 mutation." (PMID 37620636, 2023). "However, our studies in mice suggest that the consequences of heterozygous Foxj1 mutation extend to the multiciliated ependymal cells that line the ventricles of the brain and underly the observed hydrocephalus." (PMID 37620636, 2023). "Moreover, in a clinical study, six individuals with hydrocephalus were identified through whole-exome or whole-genome sequencing to be heterozygous for de novo mutations in Foxj1." (PMID 36639792, 2023). "We used the MCC-specific CEP164 knockout (FOXJ1-Cre; CEP164fl/fl) and p73 knock-out (p73−/−) mouse models, both of which exhibit a significant loss of multicilia in the ependyma of the cerebral ventricles and communicating hydrocephalus." (PMID 35248089, 2022).
Hydrocephalus (continued). "Indeed, single mutations in FOXJ1, a transcription factor that regulates cilia gene expression, reduce the number of motile cilia, and clinically associated with hydrocephalus, recurrent respiratory infections, and laterality defects." (PMID 34361034, 2021). "However, factors that disrupt multiciliated ependymal cell function often cause communicating hydrocephalus, raising questions about whether FOXJ1 mutations cause hydrocephalus primarily by blocking cerebrospinal fluid (CSF) flow or by different mechanisms." (PMID 37620636, 2023). "Thus, it is unclear whether the primary mechanism by which heterozygous mutation of FOXJ1 causes hydrocephalus is by blocking CSF flow, or whether other mechanisms are responsible." (PMID 37620636, 2023). "Interestingly, one of the reports of FOXJ1-associated hydrocephalus described a patient with enlargement of the lateral, third, and fourth ventricles, a pattern that is usually associated with communicating hydrocephalus." (PMID 37620636, 2023). "Several mutations in Ccdc39, Celsr2, Celsr3, Cetn2, Dvls, FoxJ1, Hydin, Mdnah5, Pkd1, Tg737, Daple, Dnah14, Cfap43 and Cwh43 genes, which were related to the structure or function of motile cilia on ependymal cells, have been reported to develop hydrocephalus in animal models." (PMID 33874972, 2021). "More specifically, it was shown that in order to remain differentiated, ECs need to retain the levels of Foxj1, while Foxj1 degradation results in de-differentiation and development of hydrocephalus." (PMID 40614730, 2025). "Heterozygous Foxj1 mutant mice with hydrocephalus showed increased numbers of GFAP+ cells in the ependymal layer of the lateral ventricles." (PMID 37620636, 2023). "In mice, the Foxj1-associated hydrocephalus appears to result from incomplete differentiation of multiciliated ependymal cells in the context of Foxj1 haploinsufficiency, leading to motile cilia dysfunction, disturbed CSF flow, and hydrocephalus." (PMID 37620636, 2023). "Inhibition of Foxj1-orchestrated ependymal motile ciliogenesis appears to precipitate hydrocephalus." (PMID 36639792, 2023). "The presence of hydrocephalus in FOXJ1-Cre;CEP164fl/fl mice was further confirmed by the fact that the cerebral ventricle volume as a fraction of TIV was ~ sevenfold larger than in CEP164fl/fl mice." (PMID 35248089, 2022). "We showed that FOXJ1-Cre;CEP164fl/fl mice with hydrocephalus still demonstrated sustained glymphatic transport and normal AQP4 expression along capillaries." (PMID 35248089, 2022). "Ciliopathies are often associated with neurological abnormalities and we also documented several brain aberrations in the FoxJ1-Cre;CEP164fl/fl and p73−/− ciliopathy mice including hydrocephalus." (PMID 35248089, 2022). "Hydrocephalus can also be induced through dysfunction of motile cilia on the ependymal cells by experimentally degrading the Foxj1 protein with IκB kinase-2 inhibitors." (PMID 33874972, 2021). "Two patients with chronic oto‐sino‐pulmonary disease and hydrocephalus underwent candidate testing of FOXJ1." (PMID 34132502, 2021). "Physicians treating patients with hydrocephalus and chronic oto‐sino‐pulmonary disease should be aware of this PCD association and test for FOXJ1 variants." (PMID 34132502, 2021). "In conclusion, FOXJ1 should be examined in patients with hydrocephalus and classic PCD symptoms of chronic oto‐sino‐pulmonary disease, neonatal respiratory distress, and organ laterality defects." (PMID 34132502, 2021). "FOXJ1 should be examined in patients with hydrocephalus and classic PCD symptoms of chronic oto‐sino‐pulmonary disease, neonatal respiratory distress, and organ laterality defects." (PMID 34132502, 2021). "FOXJ1 pathogenic variants cause PCD in a de novo, autosomal dominant inheritance pattern, and are associated with hydrocephalus." (PMID 34132502, 2021). "Nissl staining of P28 Foxj1 cKO mutant brain sections, tamoxifen-induced at P14, showed clear ventriculomegaly/hydrocephalus." (PMID 29695808, 2018).
Hydrocephalus (continued). "19% of FOXJ1-Cre;CEP164fl/fl mice displayed severe hydrocephalus with a prominently domed head around weaning (11 out of 58 mice); however, all FOXJ1-Cre;CEP164fl/fl adult mice examined (n = 10) showed substantial ventricular enlargement." (PMID 29244804, 2017). "For example, defects in ciliogenesis, as reported in the FoxJ1 knock-out mouse, can affect CSF dynamics in the ventricles and result in hydrocephalus." (PMID 19114013, 2008). "Whereas many of the mutations responsible for hydrocephalus have an autosomal recessive pattern of inheritance, some display X-linked (L1CAM, AP1S2) or autosomal-dominant (CFAP43, FOXJ1) inheritance patterns." (PMID 37620636, 2023). "Several reports indicate that heterozygous de novo mutations in FOXJ1 cause hydrocephalus internus, with or without chronic destructive airway disease (COPD) and randomization of left/right body asymmetry." (PMID 37620636, 2023). "Importantly, the degree of hydrocephalus in Foxj1WT/CreERT2::GFP heterozygotes was less than that observed in homozygous Foxj1 mutant mice." (PMID 37620636, 2023). "Our findings suggest that the CSF flow obstruction observed in humans harboring heterozygous FOXJ1 mutations is not the primary cause of hydrocephalus but develops secondarily." (PMID 37620636, 2023). "In summary, we showed that FOXJ1-Cre;CEP164fl/fl mice presenting with the communicating form of hydrocephalus still demonstrated sustained glymphatic transport and AQP4 water channel expression along the microvasculature was normal when assessed in the ventral hippocampus." (PMID 35248089, 2022). "In mouse models, FOXJ1 has a key role in neurogenesis and ependymal cell maturation, the alteration of which may contribute to hydrocephalus." (PMID 35011687, 2021). "Some FOXJ1 cases may lack hydrocephalus from birth, as the onset of hydrocephalus seen with FOXJ1 can be delayed for months and even occur in adulthood." (PMID 34132502, 2021). "Until recently, candidate gene testing of small numbers of subjects with clinically diagnosed PCD or hydrocephalus plus organ laterality defects did not reveal any cases associated with FOXJ1 variants." (PMID 34132502, 2021). "The mutant genes related to motile cilium dysfunction on ependymal cells, and consequent hydrocephalus development may include Ccdc39, Celsr2, Celsr3, Cetn2, Dvl, Foxj1, Hydin, Mdnah5, Pkd1, Tg737, Daple, Dnah14, Cfap43, Cwh43, Eml1, Fmn2, Tmem67, and Zcchc8." (PMID 35047005, 2021). "Considering that inheritable human mutations resulting in hydrocephalus are relatively rare, environmental exposures that tilt EC Foxj1 protein towards sustained degradation provide additional avenues to explore for understanding and treating acquired cases of hydrocephalus." (PMID 29695808, 2018). "In zebrafish and mouse, loss of Foxj1 function leads to a loss of motile, but not immotile cilia, and Foxj1 knock-out mice develop hydrocephalus postnatally." (PMID 24229449, 2013). "Heterozygous de novo mutations in the master motile ciliogenesis transcriptional regulator FOXJ1 were identified as the first autosomal dominant cause of a distinct PCD‐like condition, associated with chronic respiratory disease, laterality defects and hydrocephalus." (PMID 39115449, 2024). "Motile ciliogenesis and maturation of the ependyma depends on the forkhead transcription factor Foxj1, and, not surprisingly, de novo heterozygous mutations in FOXJ1 cause a motile ciliopathy characterized by hydrocephalus, airway disease, and deficits in right/left asymmetry." (PMID 35306341, 2022). "Nevertheless, it is important to keep in mind that TAp73 central and required role for multiciliogenesis and Foxj1 expression may also be fundamental for hydrocephalus, since disruption of Foxj1 expression in ECs induces EC transformation, ventricular breakdown, and hydrocephalus." (PMID 30930930, 2019).